TMC6 (transmembrane channel like 6)
Description:
Acts as a regulatory protein involved in the regulation of numerous cellular processes. Together with its homolog TMC8/EVER2, forms a complex with CIB1 in lymphocytes and keratynocytes where TMC6 and TMC8 stabilize CIB1 and reciprocally. Together with TMC8, also forms a complex with and activates zinc transporter ZNT1 at the ER membrane of keratynocytes, thereby facilitating zinc uptake into the ER. Down-regulates the activity of transcription factors induced by zinc and cytokines. Also plays a role in thermal sensation by inhibiting the M-channel (KCNQ2-KCNQ3 channel) current in primary sensory neurons (By similarity).
Synonyms: EVER1; EVIN1; LAK-4P; EV1; TNRC6C-AS1; lnc
Tractability: Antibody: its Gene Ontology location is reachable by antibodies, with high confidence; UniProt predicts a signal peptide or a membrane-spanning region. PROTAC: ubiquitination databases record sites on it; its protein half-life has been measured.
Gene: Protein-coding gene on chromosome 17 (78,107,397 to 78,132,579, reverse strand). Ensembl gene ENSG00000141524.
Subcellular location: Endoplasmic reticulum membrane; Golgi apparatus membrane; Nucleus membrane
Pathways (Reactome):
Immune System: Neutrophil degranulation
Gene Ontology:
Molecular function: protein binding; mechanosensitive monoatomic ion channel activity
Biological process: intracellular zinc ion homeostasis; protein stabilization; monoatomic ion transmembrane transport
Cellular component: cytoplasm; endoplasmic reticulum; extracellular exosome; Golgi apparatus; Golgi membrane; nuclear membrane; plasma membrane; specific granule membrane; tertiary granule membrane; endoplasmic reticulum membrane; membrane
Genetic constraint (gnomAD): Loss-of-function variants: 71 observed, 84.85 expected, observed/expected ratio (o/e) 0.84, 90% interval 0.69 to 1.02. The upper end of that interval is the gene's LOEUF score, 1.02, which puts it in group 4 of 6, group 1 being the genes least tolerant of losing a copy. Missense variants: 1,074 observed, 1,016.1 expected, observed/expected ratio (o/e) 1.06, 90% interval 1 to 1.11. Synonymous variants: 514 observed, 445.51 expected, observed/expected ratio (o/e) 1.15, 90% interval 1.07 to 1.24.
Homologues: Orthologues: chimpanzee TMC6 (99% identical), macaque TMC6 (95% identical), pig TMC6 (78% identical), rat Tmc6 (76% identical), guinea pig TMC6 (76% identical), mouse Tmc6 (75% identical), dog TMC6 (72% identical), tropical clawed frog tmc6 (50% identical), zebrafish tmc6a (35% identical), Caenorhabditis elegans tmc-1 (19% identical), Caenorhabditis elegans tmc-2 (18% identical). Paralogues in human: TMC5 (32% identical), TMC7 (20% identical), TMC8 (20% identical), TMC3 (19% identical), TMC2 (19% identical), TMC4 (19% identical), TMC1 (17% identical).
Diseases named in the same sentence as TMC6 in open-access papers:
TMC6 is named in the same sentence as 35 diseases in open-access papers, as found by Europe PMC text mining. Sharing a sentence is not in itself a finding about the gene and the disease. The quoted sentences say what the papers report.
epidermodysplasia verruciformis (17 papers, 2010 to 2025). A rare inherited genodermatosis characterized by chronic infection with human papillomavirus (HPV) leading to polymorphous cutaneous lesions and high risk of developing non melanoma skin cancer. "Epidermodysplasia verruciformis (EV) is typically inherited in an autosomal recessive manner, with cases linked to mutations in the EVER1/TMC6 and EVER2/TMC8 genes." (PMID 40534698, 2025). "In this case, transcriptome sequencing identified two heterozygous variants in genes classically associated with epidermodysplasia verruciformis: TMC6 (EVER1) and TMC8 (EVER2)." (PMID 40534698, 2025). "Potentially also of interest is that nonsense mutations in TMC6 cause a hereditary condition called Epidermodysplasia verruciformis involving susceptibility to human papillomavirus and resulting in cutaneous squamous cell carcinomas." (PMID 31136571, 2019). "Mutations in TMC6 underlie epidermodysplasia verruciformis, a condition in which persons are unusually sensitive to development of skin lesions caused by invasion human papilloma virus (HPV)." (PMID 26047157, 2015). "In the present study, we found that the TMC6 gene, which is associated with epidermodysplasia verruciformis (EV), and cervical cancer was highly expressed and widely distributed in DRG tissues especially in small and medium neurons." (PMID 38440182, 2024). "TMC6 and TMC8 have been reported to contribute to epidermodysplasia verruciformis, and predisposition to HPV." (PMID 38440182, 2024). "This association was first described in patients with epidermodysplasia verruciformis, a skin disease caused by an autosomal recessive disorder in the TMC6 (EVER1) and TMC8 (EVER2) genes." (PMID 37877723, 2023). "As for the other TMC molecules, mutations in TMC6 (EVER1) and TMC8 (EVER2) are implicated in epidermodysplasia verruciformis." (PMID 34429071, 2021). "In the case of patients suffering from the rare hereditary disease Epidermodysplasia verruciformis (EV), mutations within at least two genes of homologous transmembrane channel-like (TMC) proteins, TMC6 (EVER1) and TMC8 (EVER2) were described." (PMID 29770129, 2018). "Epidermodysplasia verruciformis (EV) is a rare genetic dermatological disorder inherited in an autosomal recessive manner, primarily associated with inactivating mutations in the TMC6 (EVER1) and TMC8 (EVER2) genes." (PMID 40666071, 2025). "Patients with epidermodysplasia verruciformis (EV) are particularly susceptible to HPV infection, particularly beta-HPV genotypes, due to autosomal recessive mutations in the TMC6 (EVER1) and TMC8 (EVER2) genes." (PMID 40227794, 2025). "Mutations in the EVER1 (TMC6) and EVER2 (TMC8) genes are clinically associated with autosomal recessive epidermodysplasia verruciformis (AR-EV)." (PMID 40534698, 2025).
cervical cancer (4 papers, 2012 to 2021). A primary or metastatic malignant neoplasm involving the cervix. "The EVER 1 and EVER2 genes (also referred to as TMC6 and TMC8 genes), located on the chromosome 17q25 are two of the genetic polymorphisms which were recently related to cervical cancer." (PMID 27899077, 2016). "That effort identified 8 potential genes associated with cervical cancer, including the immune genes 2′,5′ oligoadenylate synthetase gene 3 (OAS3) and sulfatase 1 (SULF1), and the epidermal dysplasia verruciformis (EV)-associated EVER1 and EVER2 genes, TMC6 and TMC8." (PMID 22496757, 2012). "In recent years, evidence has indicated that TMC6 (also known as EVER1) and TMC8 (also known as EVER2) play a role in cervical cancer and squamous cell carcinoma." (PMID 34899684, 2021).
Primary immunodeficiency (3 papers, 2016 to 2024). "We report a novel primary immunodeficiency, and a differential molecular diagnosis to CXCR4‐,DOCK8‐,GATA2‐,MAGT1‐,MCM4‐,STK4‐,RHOH‐,TMC6‐, and TMC8‐related diseases." (PMID 27896283, 2016).
viral infection (3 papers, 2010 to 2025). "Typical EV patients exhibit normal control of most viral infections; Tmc6-/-, Tmc8-/- and wildtype FVB mice similarly controlled vaccinia virus after skin challenge and induced neutralizing antibodies." (PMID 39813296, 2025). "Other viral infections, such as vaccinia, whose control also involves humoral immunity could still be cleared by Tmc6-/- or Tmc8-/- hosts given their normal humoral and partially functional cellular immune systems, as seen in classic EV patients." (PMID 39813296, 2025).
immune deficiency (2 papers, 2025). "Importantly, no mutations were detected in other known EV-associated or immunodeficiency-related genes, such as RHOH, IL7, CORO1A, STK4, DOCK8, or CARMIL2, supporting the notion that the identified TMC6 and TMC8 variants may represent the primary genetic contributors in this case." (PMID 40534698, 2025).
lung carcinoma (1 paper, 2024). "These genes include GRIA3, TAF7L, ARL14, PCDHGA9, MDGA1, ZFPM2, OSR2, TMC8/TMC6, HCN2, and CDK5R2, which are likely to be relevant in human lung cancer and are also epigenetically deregulated upon exposure to ECS in our animal study." (PMID 39273313, 2024).
metastatic cancers (1 paper, 2021). A carcinoma which has spread from the original site of growth to another anatomic site. "We also identified six genes (KHDRBS2, IQSEC1, ARHGEF1, ARID5A, IRX5, and TMC6) that were activated in metastatic cancers in two of the three cancer types and might be associated with metastatic traits." (PMID 34294701, 2021).
myeloma (1 paper, 2025). "Currently, very little is known about the transcriptional regulation of TMC6 and TMC8: their expression is high in T-cells and DNA sensing pathways activate their expression in the immortalized NIKS keratinocyte and the myeloma-derived RPMI-8226T cell lines." (PMID 41135646, 2025).
neuroblastoma (1 paper, 2024). Neuroblastoma (NB) is the most common solid, extracranial childhood tumor. "To investigate how TMC6 mediate Gαq signaling, we conducted immunoprecipitation-mass spectrometry (IP-MS) to screen for binding partners of TMC6 in ND7/23 cells, a hybridized cell line consisting of mouse neuroblastoma and rat DRG neurons." (PMID 38886367, 2024).
prostate carcinoma (1 paper, 2022). A carcinoma that arises from epithelial cells of the prostate gland. "Mutations in TMC6 (EVER1) and TMC8 (EVER2) may be involved in epidermodysplasia of the pancreas, also known as Tree Man syndrome, and increased expression of Tmc5 may be involved in the proliferation of prostate cancer." (PMID 36451105, 2022).
infection (10 papers, 2010 to 2025). The state of being infected such as from the introduction of a foreign agent such as serum, vaccine, antigenic substance or organism. "VV-luc infection peaked at a similar level around 1 week and was controlled in all mice by 2 weeks, although the signal was lowest in the Tmc6-/- mice." (PMID 39813296, 2025). "Likewise, upon percutaneous vaccinia virus challenge, both Tmc6-/- and Tmc8-/- mice controlled infection and induced vaccinia neutralizing antibody titers similarly to wildtype mice." (PMID 39813296, 2025). "This suggests that Tmc6 and Tmc8 are not restriction factors for MmuPV1 infection of murine keratinocytes, at least in vitro, as their loss would otherwise result in higher levels of MmuPV1 transcripts." (PMID 39813296, 2025). "Similarly, infection of Tmc6-/-, Tmc8-/-, and wildtype murine keratinocytes produced similar levels of viral transcripts." (PMID 39813296, 2025). "We show establishment of MmuPV1 infection is similar to wildtype FVB mice, but thereafter more persistent in Tmc6-/- or Tmc8-/- mice." (PMID 39813296, 2025). "Since wildtype FVB mice better control and clear MmuPV1 infections, we reasoned that adoptive transfer of splenocytes from wildtype FVB mice to MmuPV1-infected Tmc6-/- or Tmc8-/- mice might trigger viral clearance." (PMID 39813296, 2025). "The CD8+ T cells of wildtype, Tmc6-/- or Tmc8-/- mice responded similarly to activation by either stimulus, and these responses were not consistently impacted by MmuPV1 infection." (PMID 39813296, 2025). "Lesions were detectable in the Tmc6-/- and Tmc8-/- mice, but not in the wildtype FVB mice after vaginal challenge as the latter had controlled or eliminated their MmuPV1 infections at the time of sampling." (PMID 39813296, 2025).
cancer (5 papers, 2010 to 2023). A tumor composed of atypical neoplastic, often pleomorphic cells that invade other tissues. "Different from the classification based on amino acid sequence homology, TMC5, and TMC6 belong to the same subfamily (subfamily 2), but they showed opposite relationships with immune cells in cancers." (PMID 34899684, 2021). "The results showed that TMC4 and TMC5 have a similar expression pattern in different cancers, as do TMC6 and TMC7." (PMID 34899684, 2021). "We also report an association between genes in EVER1/TMC6 and EVER2/TMC8 and a SNP that lies between the two genes with progression to CIN3/cancer." (PMID 20084279, 2010). "Further, TMC4, TMC5, TMC6, TMC7, and TMC8 were tissue-specifically and cancer-specifically expressed." (PMID 34899684, 2021).
genodermatosis (3 papers, 2012 to 2024). "Congenital epidermodysplasia verruciformis (CEV) is a Genodermatosis linked to different inheritance patterns and mutations of the EVER1/TMC6 and EVER2/TMC8 genes." (PMID 39001899, 2024).
tumour (2 papers, 2015 to 2021). "An inter-chromosomal rearrangement occurred between chromosome 17 and chromosome 1 was identified in patient WG04, in both primary and metastasis tumours, which results in a novel gene–gene fusion involving TMC6 and IQGAP3, with reversed 5′ and 3′ orientation." (PMID 26647728, 2015). "Some abnormally regulated genes in our prognostic signature participated in tumour initiation and development, including NUMB, RSRC2, TMC6, CASP8, TRIO, and COMMD5." (PMID 34772375, 2021).
genetic disease (1 paper, 2021). "EV, described by Lewandoswsky and Lutz in 1922, is an autosomal recessive genetic disease characterized by a mutation in the TMC6 (EVER1) and TMC8 (EVER2) genes, which leads to chronic infection by specific types of HPVs, mainly of the beta genus." (PMID 33341319, 2021).
TMC6 also shares sentences with these, for which no sentence is quoted: skin carcinoma (2 papers); ataxia telangiectasia (1); bacterial infections (1); bare lymphocyte syndrome (1); breast carcinoma (1); chronic myeloid leukemia (1); Clouston syndrome (1); combined immunodeficiency (1); cutaneous squamous cell carcinoma (1); cystic fibrosis (1); endometrial cancer (1); gynecologic cancers (1); immunodeficiency (1); leukocyte adhesion deficiency (1); Netherton syndrome (1); pancreatic cancer (1); psoriasis (1); skin disorder (1); squamous cell carcinoma (1); WHIM syndrome (1).